MMP13 (matrix metallopeptidase 13)
Diseases named in the same sentence as MMP13 in open-access papers (continued):
Sharing a sentence is not in itself a finding about the gene and the disease.
breast carcinoma (continued). "The data suggest that MMP13-selective inhibitors, which lack musculoskeletal side effects, may have therapeutic potential both in primary breast cancer and cancer-induced bone osteolysis." (PMID 22253746, 2012). "Together, these results indicate critical involvement of MMP13 in clinical breast carcinoma." (PMID 22253746, 2012). "MDA-MB-231 breast cancer cells secreted higher levels of MMP-13 than less aggressive MCF7 cells." (PMID 22032644, 2011). "Both MMP-13 and TIMP-3 have been implicated in breast cancer." (PMID 19405959, 2009). "MMP13 (collagenase-3) was originally identified in human breast cancer tissue." (PMID 18698413, 2008). "Interestingly, a recent study reported upregulation of several MMPs, including MMP13, at the transition from non-invasive to invasive breast cancer cells in an in vitro model." (PMID 18698413, 2008). "Our results suggest that MMP13 is a marker of carcinoma-associated myofibroblasts of invasive carcinoma, even though it does not make a major contribution to tumor progression in the MMTV-PyMT breast cancer model." (PMID 18698413, 2008). "Therefore, the role of MMP13 in breast cancer needs to be further studied." (PMID 40243781, 2025). "However, MMP13 expression scores are not linked with the prognosis of breast cancer patients’ survival using TCGA-BRA, SCAN-B, or METABRIC cohorts." (PMID 34072157, 2021). "However, the clinical utility of MMP-13 as a breast cancer marker remains controversial." (PMID 34452576, 2021). "Upregulation of Sp7 in breast cancer cells is associated with increased invasion and bone metastasis, and this may occur by upregulation of ECM modifying metalloproteinases, MMP9 and MMP13, and other factors that increase vascularization, and affect bone cell function." (PMID 32755539, 2020). "Additionally, we found genes highly expressed in breast cancer stroma in the Human Protein Atlas (EGR1, OSBPL8, FAM171A2, FGD6, and CEP131), or likely expressed in fibroblasts (MMP13), that are reported to play a role in breast cancer progression among the most important ones." (PMID 31505876, 2019). "Similarly, Mmp13 has been connected to increased breast cancer metastasis." (PMID 31505876, 2019). "Indeed, our study suggests an important interplay of ETV4 and MMP13 in human breast cancers that could, together, be assessed for their possible signature for guiding diagnosis or therapeutics." (PMID 29996935, 2018). "As an example, MMP-9 is elevated in breast cancer patients, including tumor cells; additionally, serum, plasma, and urine may be also useful for early cancer diagnosis and metastasis prediction, and MMP-13 correlates with aggressiveness of the tumor and poor prognosis in HER2-positive tumors." (PMID 26404249, 2015). "Therefore, in this study we sought to determine whether direct in vivo genetic manipulation of host MMP-13 alters collagen I organization at the mammary tumor-host boundary (i.e. TACS), with demonstrable effects on tumor metastasis." (PMID 24010522, 2013). "Thus, MMP13 inhibition may affect both the growth and osteolytic consequences of breast carcinoma cells metastasized to bone." (PMID 22253746, 2012). "Another explanation for MMP-13 effect on osteoclastogenesis could be an indirect action on osteoblasts; it is often thought that MMPs and other osteogenic factors secreted by breast cancer cells activate osteoclasts through osteoblasts by changing the expression of RANKL and/or OPG." (PMID 22032644, 2011). "However, while MMP-13 might represent a poor prognosis marker in breast carcinomas it seems unlikely that tumour aggressiveness and bone metastatic lesions solely depend on its digestive function in the bone microenvironment." (PMID 22032644, 2011). "Interestingly, the clinical utility of MMP-13 as a breast cancer marker remains controversy." (PMID 18373849, 2008).
breast carcinoma (continued). "This is different from the conventional findings that gremlin-1 (GREM1) can facilitate breast cancer pulmonary metastasis via a signal transducer and activator of transcription (STAT) 3-mediated MMP13 regulation." (PMID 40243781, 2025). "The destruction of triple-helical collagen by MMP13 not only facilitates ECM remodelling, but also enhances the migration and metastasis of breast cancer cells." (PMID 40243781, 2025). "This positive feedback loop, driven by elevated MMP13 levels, further promotes TAM infiltration and angiogenesis, and ultimately contributes to the rise in breast cancer tumour temperatures." (PMID 40243781, 2025). "MMP13 reduces the stiffness of the ECM through degradation, which provides a softer microenvironment and is beneficial for the survival of disseminated breast cancer cells at secondary sites." (PMID 40243781, 2025). "Under the action of MMP13, the structure and plasticity of the ECM are changed, creating conditions for the metastasis of breast cancer-related cells." (PMID 40243781, 2025). "We also showed that pharmacological inhibition of MMP-13 in zebrafish, rats, and mice rescues paclitaxel neurotoxicity and restores epidermal integrity and that MMP13 is upregulated in the skin of breast cancer survivors with CIPN following paclitaxel therapy." (PMID 40894047, 2025). "In breast cancer, elevated ATF3 expression induces the expression of MMP13, TWIST, Slug, and Snail, thereby modulating tumor metastasis." (PMID 38586033, 2024). "In breast cancer patients, expression of the POU class 1 homeobox 1 transcription factor (Pit-1) was positively correlated with the presence of both MMP1 and MMP13." (PMID 36677584, 2023). "This is achieved through the secretion of ANGPTL4, MMP13, and STC1 by CAFs, which promotes breast cancer growth." (PMID 38273859, 2023). "Expression of the POU class 1 homeobox 1 transcription factor (Pit-1) in breast cancer patients was positively correlated with the presence of both MMP1 and MMP13." (PMID 36677584, 2023). "Knocking down Osx suppresses breast cancer invasion and osteolytic metastasis by downregulating MMP9, MMP13, VEGF, IL-8, and PTHrP, indicating the involvement of Osx in breast cancer invasion, angiogenesis, and bone resorption." (PMID 38041134, 2023). "To confirm the regulatory role of SRF in MMP gene expression in breast cancer cells, we used two different SRF-targeting siRNAs to knock down SRF and quantified the levels of MMP-9 and MMP-13 mRNAs using real-time RT-qPCR." (PMID 37266453, 2023). "CADD522 negatively regulated RUNX2 target gene transcription including MMP13, VEGF and SLC2A1 in breast cancer cells." (PMID 36936386, 2023). "In breast cancer, the positive regulation of metastasis through the ABL/RUNX2/MMP13 axis has been reported." (PMID 35805994, 2022). "These compounds are predicted to stably interact with the MMP12, CDK4, JAK3, VEGFR2, MMP13, VEGFR1, and KCNA3 proteins, which have a role in inhibiting the growth and inducing apoptosis in breast cancer cells." (PMID 36106139, 2022). "Proteomics data for breast cancers in revealing CTHRC1 overexpression with POSTN and MMP13 further strengthens the need to look at this gene network in other cancers." (PMID 36190948, 2022). "In breast cancer tumour samples CTHRC1 protein levels are significantly upregulated with POSTN and MMP13, further supporting the need to evaluate their crosstalk in cancers." (PMID 36190948, 2022). "Breast Cancer: curcumin down regulate of NF-jB, AP-1, COX-1, and –2, VEGF, fibroblast growth factor (FGF), cyclin E, IL-6, and –11, TGF-b, MMP-2, MMP-9, and MMP-13, the upregulation of tissue inhibitor of metalloproteinase-1." (PMID 36712505, 2022). "Meanwhile, RUNX2 expression was increased by increasing the expression of vascular endothelial growth factor, matrix metalloproteases (MMP2, MMP9, and MMP13), and bone sialoprotein (BSP) in breast cancer metastatic cells." (PMID 36092942, 2022).
breast carcinoma (continued). "Overexpression of MMP-13 mediated by GOLM1, C1r and Leptin has been shown to increase tumour growth in breast cancer, cutaneous squamous cell carcinoma and pancreatic cancer." (PMID 35805035, 2022). "This when considered with the known role for MMP13 in bone metastasis of breast cancer strongly supports a role for CTHRC1-POSTN-MMP13 crosstalk in mediating the same." (PMID 36190948, 2022). "We showed that RUNX2-mediated MMP13 expression lies downstream of ABL and that depletion of ABL in breast cancer cells inhibits invasive ability." (PMID 34136397, 2021). "Further investigations indicated that upon co-culturing, breast cancer cells secreted CSF1 to induce expression and release of CXCL7 from monocytes, which in turn acted on cancer cells to promote FAK activation, MMP13 expression, migration, and invasion." (PMID 34789744, 2021). "Treatment with recombinant CXCL7 protein enhanced chemotaxis of monocytes and promoted migration and invasion of breast cancer cells through FAK- and MMP13-mediated pathways." (PMID 34789744, 2021). "Collectively, these results suggest that an increase in MMP13 expression by GREM1 occurs through STAT3 activation and that this GREM1-STAT3-MMP13 axis is important for promoting the migration and invasion of breast cancer cells." (PMID 33287358, 2020). "In our previous study, we confirmed that GREM1 promotes breast cancer proliferation through EGFR activation, so we confirmed that the increase in MMP13 expression by GREM1 is through EGFR activation." (PMID 33287358, 2020). "Studies have shown that P2 × 7 receptor activation can promote the migration and metastasis of breast cancer cells by activating AKT signal and regulating the expression of MMP-13 and E-cadherin expression." (PMID 33330466, 2020). "Knockdown of Osx inhibited the invasive capacity of breast cancer cells and osteolytic metastasis by downregulating MMP9, MMP13, VEGF, IL-8, and PTHrP, whereas overexpression of Osx had the opposite effect." (PMID 30631043, 2019). "By downregulating MMP9, MMP13, VEGF, IL-8, and PTHrP, knockdown of Osx inhibited invasion of breast cancer cells and osteolytic metastasis; overexpression of Osx had the opposite effect." (PMID 30631043, 2019). "In particular, miR-21, MMP1, MMP9, MMP13, CXCR4 and vimentin were found overexpressed in the invasive margins of breast cancer tissues of clinical samples and in the cancer cell lines; E-Cadherin, on the other hand, was decreased." (PMID 31362429, 2019). "Up-regulated expression of COL10A1, MMP11, CST1, GJB2, MMP1, MMP13, and CEACAM6; down-regulated expression of ADH1B, CIDEC, THRSP, GPD1, TIMP4, FABP4, and SCARA5 genes was common in breast cancers of the two populations." (PMID 31292488, 2019). "QPCR analysis confirmed the up-regulated expression of MMP1, MMP13, and MMP11 genes and down-regulated expression of ADAMTS1 and ADAMTS5 genes in breast cancers observed in the microarray experiments." (PMID 31292488, 2019). "In our study, we detected some published potential biomarker of breast cancer bone metastasis, or their function has been reported in breast cancer bone metastasis such as SPARC, IBSP, MMP9, MMP13." (PMID 30918839, 2019). "Knockdown of Osx inhibited invasion of breast cancer and osteolytic metastasis by downregulating MMP9, MMP13, VEGF, IL-8, and PTHrP, which are involved in invasion, angiogenesis, and osteolysis; overexpression of Osx had the opposite effect." (PMID 30631043, 2019). "CTSG is also capable of activating pro-MMP-9, that cleaves and releases active transforming growth factor-β (TGFβ), MMP-13 and RANKL at the tumor-bone interface of mammary tumor-induced osteolytic lesions." (PMID 31647805, 2019). "MiR-148a inhibits breast cancer migration, invasion and angiogenesis by suppressing WNT-1, MMP-13, ERBB3." (PMID 29743122, 2018).
breast carcinoma (continued). "This fact, together with the important role of certain cellular targets of dasatinib in the regulation of the dissemination and seeding of breast cancer cells, led us to explore the effect of this kinase inhibitor in NRG‐induced MMP13 upregulation." (PMID 29032615, 2017). "Mechanistic studies led to the identification of matrix metalloproteinase 13 [MMP13, also termed collagenase‐3] as an important mediator of metastatic dissemination in breast cancer cells in which the NRG–HER signaling axis was active." (PMID 29032615, 2017). "Recent studies in gastric carcinoma, breast cancer and chondrosarcoma cells exemplify the Src-FAK-mediated regulation of MMPs like MMP9 and MMP13 via activation of AP-1 transcription factors like c-Jun and c-Fos." (PMID 26001294, 2017). "Consistently with its inhibitory effect on EMT, 1,25(OH)2D3 downregulates the secretion of MMP2, MMP9, and MMP13 in prostate, breast, pancreatic, and squamous cell carcinoma cells and increases TIMP1 and TIMP2 activity in prostate and breast cancer cells." (PMID 26880977, 2016). "Expression of the double or triple mutants of RUNX2 in breast cancer cells reduces the mRNA levels of two metastasis-related target genes, MMP9 and MMP13, and reduces the RUNX2-dependent invasive potential of breast cancer cells." (PMID 26204939, 2015). "To test this possibility we silenced the expression of MMP13 in breast cancer cells expressing both RKIP and Erk2Q103A.The effect of MMP13 silencing was evaluated by an in vitro invasion assay." (PMID 26308852, 2015). "In this study using two near-isogenic mouse mammary tumor cell lines, 168FARN and 4T1, and human breast cancer cell line MDA-MB231, we demonstrated that the expression of RKIP negatively correlated with that of MMP13." (PMID 26308852, 2015). "Although three factors, namely CCL5, IL6, and MMP13 are up-regulated during the interaction, in vitro and in vivo studies indicate that CCL5 is the key contributor to the metastatic characteristics of breast cancer." (PMID 25072326, 2014). "In breast cancer patients, expression of Pit-1 was found to be positively correlated with the presence of both MMP-1 and MMP-13." (PMID 25527274, 2014). "Our data indicates that Pit-1 regulates MMP-1 and MMP-13, and that inhibition of MMP-13 blocked invasiveness to lung in Pit-1-overexpressed breast cancer cells." (PMID 25527274, 2014). "In the MCF-7 and MDA-MB-231 human breast cancer cell lines, we showed that Pit-1 regulates MMP-1 and MMP-13." (PMID 25527274, 2014). "Given that these MMPs have been related to breast cancer metastasis, we explored the effect of Pit-1 overexpression and MMP-1 or MMP-13 knockdown in an SCID mouse xenograft tumor model." (PMID 25527274, 2014). "In this study, the mRNA and protein levels of MMP-2, MMP-9, MMP-13, MT1-MMP and TIMP-2 in benign and malignant mammary tumors were thoroughly analyzed." (PMID 21726449, 2011). "The highly invasive MDA-MB-231 breast cancer cell line expresses TLR9, which promotes tumour cell invasion by increasing the activity of MMP-13." (PMID 20145615, 2010). "The expression of two genes, Matrixmetalloproteinase-13 (MMP-13) and Matrixmetalloproteinase-9 (MMP-9), that are known to be involved in invasion and have been shown to be regulated by Runx2 in metastatic breast cancer cells, was examined." (PMID 20591170, 2010). "Similar significant differences between normal breast tissue and grade 2 breast cancer tissue concerning the mRNA levels were observed for MMP-9 (p = 0,0127), MMP-11 (p = 0,0007) and MMP-13 (p = 0,008)." (PMID 19531263, 2009). "During progression of mammary carcinomas in the polyoma virus middle T oncogene mouse model (MMTV-PyMT), Mmp13 mRNA was strongly upregulated concurrently with the transition to invasive and metastatic carcinomas." (PMID 18698413, 2008).
breast carcinoma (continued). "Matrix metalloproteinase-1 was immunohistochemically detected in 88.3% of breast carcinomas, MMP-2 in 42%, MMP-7 in 87.4%, MMP-9 in 74%, MMP-11 in 89.3%, MMP-13 in 73.3%, MMP-14 in 90%, TIMP-1 in 95%, TIMP-2 in 87% and TIMP-3 in 82.3%." (PMID 17848954, 2007). "Under these conditions, four secreted MMPs were identified: MMP-1, MMP-3, MMP-9, and MMP-13 and the membrane-anchored MMP, MT1-MMP in all 3 breast cancer cell lines (MDA-231 cells shown, results similar in all 3 breast cancer cell lines)." (PMID 15701164, 2005). "The relationship between expression of MMP-13 and TIMP-1 and the mode of tumor invasion [MI] was evaluated immunohistochemically, using breast carcinoma tissue as a positive control." (PMID 15291964, 2004). "In co-cultures of breast cancer cells and monocytes, breast cancer cells secrete CSF1 and induce monocytes to express and release CXCL7, which in turn acts on cancer cells to promote FAK activation, MMP13 expression, migration, and invasion." (PMID 36407100, 2022). "In breast cancer, CTHRC1 gene and protein expression is upregulated with MMP13 and POSTN." (PMID 36190948, 2022). "Previous studies showing that MMP13 is required for invasion and metastasis of breast cancer cells prompted us to query whether the ABL-RUNX2 transcriptional complex potentiated breast cancer invasion." (PMID 34136397, 2021). "A similar relationship was observed in breast cancer, but for ETV4 and MMP13." (PMID 33648461, 2021). "MMPs, such as MMP13 and urokinase plasminogen activator (uPA) are also transcriptionally regulated by ETV4, which are involved in the ETV4-driven malignant phenotypes in prostate cancer and breast cancer." (PMID 32018225, 2020). "Importantly, the expression of MMP13 and ETV4 messenger RNA was characterized in 456 breast cancer samples." (PMID 29996935, 2018). "Moreover, MMP13 can activate MMP9 and TGFβ to increase the local expression of RANKL at the tumor-bone interface in breast cancer." (PMID 26863138, 2016). "Similarly, in human breast cancer, RUNX2 directly regulates the expression of MMP9 and MMP13, bone sialoprotein and OPN, IL-8 and the TGFβ-induced PTHrP levels and mediates invasion of the human breast cancer cell lines MDA-MB-231 and MCF7." (PMID 26204939, 2015). "In addition, it also remained conflicting as to the influence of MMP-1, MMP-2, MMP-11, MMP-13 and MMP-14 expression on the survival of breast cancer patients." (PMID 26270045, 2015). "Overall, these findings suggest that ANGPTL2 may promote breast cancer progression, possibly by activating CXCR4 and MMP-13." (PMID 25773070, 2015). "Expression of MMP13 has no observable effect on inhibition of intravasation, extavasation and lung colonization associated with the expression of RKIP in breast cancer cells." (PMID 26308852, 2015). "Similarly, another study to elucidate the mechanism for breast cancer migration and metastasis indicated that the metastasis promoted by CCL5 and CCL9 was inhibited by inhibitors of their downstream target MMP13." (PMID 25072326, 2014). "Consistent with other reports, MMP13 KO did not alter mammary tumor size in our E0771 mammary tumor model." (PMID 24010522, 2013). "The fact that MMP13 KO results in TACS-1 collagen patterning similar to what others have seen in “early stage” tumors in their mammary tumor models suggests that the lack of MMP13 prevents the tumor stroma from progressing to a “late stage” structure." (PMID 24010522, 2013). "Another study highlights the role of TLR9 in highly invasive MDA-MB-231 breast cancer cell line which when activated promotes MDA-MB-231 cell invasion by increasing the activity of matrix metalloproteinase 13 (MMP13), but not MMP8." (PMID 22295250, 2012). "Also interesting is the parallel to studies on MMP-13 and uPA in the murine MMTV-PyMT breast cancer model." (PMID 21326869, 2011).